EGFR (epidermal growth factor receptor)
Diseases named in the same sentence as EGFR in open-access papers (continued):
Sharing a sentence is not in itself a finding about the gene and the disease.
cancer (continued). "However, this ratio is acceptable, since most cancer types were adenocarcinomas, and this is compatible with the findings of another study investigating the association between adenocarcinoma and EGFR mutation in Taiwan." (PMID 29447182, 2018). "As a rule, EGFR-dependent cancer cell lines that have undergone EMT as a mechanism of acquired resistance fail to exhibit previously documented molecular events such as selection for the EGFR T790 M gate-keeper mutation or MET amplification." (PMID 29458371, 2018). "In fact, both the overexpression and mutation of EGFR eventually led to the phosphorylation and concomitant activation of downstream signaling, promoting the proliferation, metastasis, and resistance to chemotherapy in cancer cells." (PMID 29472856, 2018). "Thus, a single ERBB inhibitor has been developed for treating EGFR-mutated or HER2-amplified cancers." (PMID 29950679, 2018). "Gene mutations affecting EGFR members have been associated with several cancers." (PMID 29455662, 2018). "EGFR is a host factor that has been found to play essential roles in several bacterial infections recently, although it was widely reported previously to be associated with different cancers." (PMID 30687645, 2018). "Similarly, overexpression of EGFR has been implicated as significant in these cancer types and various others." (PMID 29541406, 2018). "EGFR mutation might be among the carcinogenic mechanisms in the development of cancer in smokers with activating EGFR mutation." (PMID 30055587, 2018). "Hence, many cancers of epithelial origin, e.g. head and neck, colorectal and lung tumors, are characterized by EGFR overexpression or mutated EGFR forms." (PMID 29876011, 2018). "This underlines the potential of EGFR as a promising target for cancer immunotherapy." (PMID 29876011, 2018). "However, cancer cells can develop resistance to these agents with prolonged exposure; in over 50% of cases, this is attributable to the EGFR T790M mutation." (PMID 28422737, 2017). "NSCLC represents the leading cause of cancer death throughout the developed world, but the introduction of a novel class of targeted anti-neoplastic agents, EGFR and ALK TKI directed against EGFR and ALK, has significantly changed the therapeutic options available for patients with NSCLC." (PMID 29312572, 2017). "The aberrant activation of EGFR is implicated in a variety of human cancers." (PMID 28574446, 2017). "EGFR was also transported in the nucleus, and nuclear localized EGFR is strongly associated with disease progression and worse overall survival in numerous cancers." (PMID 28056982, 2017). "However, acquired resistance is generally caused by the emergence of cancer cells clones with activated mutations in components of the EGFR pathway in order to reactivate this pathway." (PMID 29137301, 2017). "The epidermal growth factor receptor plays crucial roles in cellular processes such as cell proliferation and differentiation, and its aberrant activation is implicated in a variety of human cancers." (PMID 28574446, 2017). "Monoclonal antibodies interfering with the signalling of the hepatocyte growth factor receptor encoded by the MET oncogene and of the epidermal growth factor receptor (EGFR) encoded by the HER1 gene have received approval for the treatment of various types of cancers." (PMID 28182330, 2017). "Some studies have verified that EGFR mutations can be regulated by miRNA in cancer therapies." (PMID 28430586, 2017). "EGFR mutations have potential application in diagnosis and therapy of various human cancers." (PMID 28537895, 2017). "The epidermal growth factor receptor (EGFR) is recognized as an important molecular target in cancer therapy, and somatic activating mutations of the EGFR gene (EGFR mutations) are known as one of the oncogenic driver mutations in non small cell lung cancer (NSCLC)." (PMID 28424065, 2017).
cancer (continued). "The authors analyzed the response of 7 CRC cell lines to cetuximab as well as primary tumors, liver and lung metastasis from 25 CRC patients treated with cetuximab or panitumumab, by evaluating NGS (Illumina) mutation profiles of 48 cancer-related genes, EGFR and E-cadherin expression." (PMID 29221448, 2017). "We next investigated whether PEG engagerEGFR can enhance the anti-proliferation activity of a drug-loaded nanocarrier in different type of cancer cells that express either wild-type EGFR or mutated EGFR." (PMID 28593948, 2017). "TKIs are effective against cancer cells with EGFR L858R mutation and exon 19 deletion." (PMID 28513565, 2017). "The EGFR sequence is frequently altered in multiple cancers, and if B-Myb indeed regulates A3B expression and somatic mutations are mediated via EGFR activity, this could favor the clinical tack of inhibiting EGFR signaling in cancer therapeutics." (PMID 28276478, 2017). "However, administration of pemetrexed in first-line setting in EGFR-mutated cancers is an unlikely scenario in the current era." (PMID 29201462, 2017). "Although EGFR TKI can benefit patients with EGFR mutation, drug resistance is still unavoidable, Intratumor heterogeneity may be the lead culprit of cancer resistance, and introduce significant challenges in designing effective treatment strategies." (PMID 29088904, 2017). "EGFR signalling has been linked to cancer development but whether it has any role in pre-metastatic niche formation is not known." (PMID 28393839, 2017). "The EGFR pathway is activated by either mutation or overexpression in a wide variety of cancers." (PMID 29069801, 2017). "One of the possible mechanisms for acquired resistance to EGFR-TKIs can be explained by the occurrence of secondary mutations in the EGFR gene and activation of redundant receptor proteins such as Met and Axl in several human cancers." (PMID 29190951, 2017). "Finally, our results indicate that cancer associated body fluids (pleural, pericardial or cerebrospinal fluid) are certainly a suitable source for biomarker testing that can extend EGFR mutation detection to biofluids other than blood." (PMID 28947971, 2017). "AKT proteins are serine/threonine-protein kinases that play key roles in AKT-mTOR pathway, which is downstream of EGFR and implicated in multiple biological processes relevant to drug resistance, including cancer cell metabolism, proliferation, survival and growth." (PMID 28801576, 2017). "By using univariate regression analysis, we found that the risk of cancer-related death was significantly increased by the presence of EGFR CNG (OR =4.14, 95% CI =1.94-8.86, P <0.001), HER3 CNG (OR =2.48, 95% CI =1.15-5.40, P =0.02) and HER4 CNG (OR =2.16, 95% CI =1.02-4.58, P =0.04)." (PMID 29190914, 2017). "However, overexpression of EGFR has been associated with tumor growth and progression in a variety of cancers including non-small cell lung cancer (NSCLC), head and neck squamous cell carcinoma, and pancreatic cancer." (PMID 29250520, 2017). "A failure to adequately induce RNase 7 may contribute to the increased cutaneous infection risk of cancer patients receiving anti-EGFR therapy." (PMID 29066761, 2017). "Moreover, several exon 20 insertion mutations in the HER2 gene, such as EGFR mutations, are known to be found in cancer." (PMID 29140271, 2017). "Of relevance is the recent demonstration that the interaction of ITGβ4 and epidermal growth factor receptor (EGFR) is associated with poor prognosis in cancer patients since epidermal growth factor (EGF)-dependent signals stimulate ITGβ4-mediated migration of metastatic cells." (PMID 28512118, 2017).
cancer (continued). "The EGFR gene is frequently mutated or overexpressed in lung, colon, head and neck, brain, pancreatic, and breast cancers, and which promotes tumor progression and drug resistance in these cancers." (PMID 29261144, 2017). "Moreover, the evidence suggests that cross-talk among the signalling cascades of COX-2-derived PGE2, loss of E-cadherin and EGFR activation enhances the cancer cell proliferation, EMT program and metastasis." (PMID 28740192, 2017). "Only a mutated form of the EGFR, known as EGFRvIII, can cause cancer." (PMID 28970798, 2017). "Moreover, all the cancer related sequence variants included in well-curated databases were structurally mapped in different EGFR kinase domain conformations." (PMID 29228029, 2017). "Mutations in EGFR represent one of the most common actionable targets for cancer treatment." (PMID 28472989, 2017). "Moreover, the inhibitory effect of lapatinib on EGFR/ErbB2 signaling in the sensitive condition was found to be associated with glucose starvation of cancer cells, and thus induced cancer cell death." (PMID 28288164, 2017). "EGFR TKIs are key drugs for patients with EGFR mutation-positive cancer." (PMID 28740574, 2017). "A vast variety of researches showed that estrogen receptor (ER), progesterone receptor (PR), human epidermal growth factor receptor 2 (HER2), and EGFR presence uncovered by immunohistochemistry (IHC) is associated with cancer cell differentiation or development." (PMID 28938549, 2017). "In addition, genetic alterations affecting several bona fide cancer genes, including mutations and amplifications in EGFR, were more common in PTs, particularly in malignant lesions." (PMID 28267263, 2017). "However, it is unclear how the mutational status, gene copy number and EGFR overexprresion impacts signaling pathway in cancer." (PMID 28938010, 2017). "Moreover, this protein-protein interaction network also indicated that HNRNPK was physically interacted with many other critical cancer associated genes such as EGFR, CD81 and AURKA." (PMID 29262567, 2017). "Notably, abundant studies also indicate that EGFR activation is a causal driver of many cancers, including breast, lung, brain, and colourectal cancers." (PMID 28272528, 2017). "Various studies have implicated the overexpression of EGFR in the progression of cancer." (PMID 29246028, 2017). "EGFR is over-expressed and/or frequently mutated in many human cancers." (PMID 28262749, 2017). "In addition, there was a direct association between PARP1 and the key cancer gene of NSCLC: EGFR, ALK in the interaction network of genes." (PMID 29152079, 2017). "However, activation of the EGFR signaling pathway in cancer cells has been linked not only with increased cell proliferation but also with angiogenesis, metastasis, and decreased apoptosis." (PMID 28832537, 2017). "EGFR is frequently overexpressed and/or mutated in cancer, resulting in increased activation of cell proliferation and pro-survival pathways thus rendering EGFR an excellent target for cancer therapy." (PMID 28572590, 2017). "We hypothesized MSI leads to mutations in DNA repair proteins including BRCA2 and cancer drivers including EGFR." (PMID 28591715, 2017). "In addition, miss-regulation of EGFR activity has been associated with cancer and metastasis, and is a target for therapies." (PMID 28678789, 2017). "Most of these mutations occur in signal transduction-related kinases, including HER2, KRAS, AKT1, MEK, and EGFR, and they cause constitutive kinase activation, thereby inducing aberrant cancer cell growth and metastasis, which lead to poor prognoses and poor patient treatment responses." (PMID 29132432, 2017).
cancer (continued). "Moreover, c-Met was found to induce ErbB3 signalling in cancer cells and the inhibition of both, c-Met and EGFR caused cancer cell death." (PMID 28417948, 2017). "However, the underlying mode of action of how EGFR antagonist application can explain its clinical efficacy in different types of cancers remains largely unresolved." (PMID 28970798, 2017). "Finally, our results indicate that cancer associated body fluids are certainly a suitable source for biomarker testing that can extend EGFR mutation detection to bio-fluids other than blood." (PMID 28947971, 2017). "When ERL binds to the EGFR's extracellular domain, the receptor dimerization took place, which further autophosphorylates the critical tyrosine residues on the cytoplasmic terminal implicated in cell proliferation and the survival of cancers." (PMID 27726288, 2016). "Epidermal growth factor receptor (EGFR) gene mutations occur in multiple human cancers; therefore, the detection of EGFR mutations could lead to early cancer diagnosis." (PMID 27223277, 2016). "However, we found that cancer cell-lines with MAP3K4 A1199 deletion hotspot mutations were more resistant to all four examined EGFR inhibitors (Erlotinib, Lapatinib, TKI258 and AZD0530) in comparison to cancer cell-lines without MAP3K4 mutations." (PMID 27356755, 2016). "Then, guided by recent findings indicating that some CD16A polymorphisms predict the therapeutic effectiveness of cetuximab in EGFR+ cancer patients, we found that only CD16A-48H gene variant is involved, being more associated with CRC patients and advanced stages of CRC." (PMID 27519478, 2016). "We believe that this structural information will be a rational basis for future investigations to unravel the overall working mechanism of EGFR trafficking, which has received great interest due to its direct association with cell survival and cancer signaling." (PMID 26866605, 2016). "Furthermore, it had experiments demonstrated dysregulation of the EGFR pathway was associated with growth and invasion in cancer." (PMID 27634882, 2016). "Extracellular, intracellular, and mutated EGFRs have been therapeutic targets in cancer for some time and the ability to quantify expression levels could be used to identify patients that would benefit from anti-EGFR therapies." (PMID 27388754, 2016). "We realized that additional gene mutations may coexist with KRAS or EGFR mutations in cancer cells and may also affect the function of ZEB1." (PMID 27456471, 2016). "Furthermore, mutations in EGFR/MAPK pathway and associated resistance to anti-EGFR therapies are, in fact, linked to the metabolic alterations described by Otto Warburg in cancer cells." (PMID 27323830, 2016). "Indeed, EGFR-associated tumors have been targeted by specific blocking antibodies or inhibitors for cancer treatment." (PMID 27833557, 2016). "Moreover, downregulation of the IL-1 pathway using the IL-1ra was shown to alleviate cancer-associated cachexia and EGFR inhibitor-induced skin toxicity." (PMID 27738319, 2016). "The autonomous and dysregulated activation of EGFR is implicated in most cancers." (PMID 27058423, 2016). "It is possible that these SNPs are associated with increased receptor activation, EGFR expression or stability, which could increase cancer risk by promoting cell proliferation." (PMID 27437777, 2016). "In recent analyses, COSMIC mutations in the case of EGFR and also for all genes showed an uneven distribution of missense substitutions among cancer driver mutations defined as reoccurring mutation compared to likely passenger mutations recorded only once in COSMIC." (PMID 27150584, 2016).
cancer (continued). "This suggests that EGFR auto‐activation or EGFR overexpression resulted from genetic mutation that occurs frequently in cancer genesis and development may be also a risk for cardiac diseases, despite that no tumourigenesis was observed in heart." (PMID 26762600, 2016). "Overexpression of EGFR signaling has been linked to the majority of cancers." (PMID 26881213, 2016). "Because EGFR signaling is an important pro‐survival factor in cancer cells, we have been suggested that by down‐regulating EGFR expression, miR‐134 might play an inhibitory role in cancer cell proliferation." (PMID 27241841, 2016). "Indeed, cancer invasiveness is stimulated by numerous mechanisms, including activating EGFR mutations." (PMID 27999344, 2016). "ErbB receptor tyrosine kinases (EGFR/ErbB1, ErbB2, ErbB3 and ErbB4) are known to activate cellular transformation, migration, and proliferation, and they are also implicated in development and progression of several cancer types." (PMID 27029001, 2016). "The deregulated EGFR signaling pathway associated with cancer malignancy isoften found in HNSCC." (PMID 27510965, 2016). "EGFR transactivation through this mechanism has been implicated in the regulation of many normal cell functions and the growth, development and progression of many diseases such as cancers, kidney disease, and cardiovascular disease." (PMID 26771606, 2016). "This may be explained by the fact that different genetic variants in EGFR could have different functional properties that influence prognosis in various cancers." (PMID 27437777, 2016). "Our results revealed that Asp-UA could inhibit EGFR-mediated pathway through increasing or decreasing the expression of proteins associated with cancer metastasis." (PMID 27683033, 2016). "In particular, since highly immunogenic T cell epitopes have been identified from wild-type and mutant EGFR, their clinical application as a novel immunotherapy might be promising for treatment of EGFR-associated cancer." (PMID 27833557, 2016). "Moreover, the molecular mechanism of SCD1 in promoting the proliferation of cancer cells was shown to be associated with inhibition of EGFR signal pathway." (PMID 27223066, 2016). "The EGFR is deregulated, in several types of cancer, by three fundamental mechanisms: (i) activating gene mutations; (ii) overexpression of the EGFR trans-membrane form (via gene amplification or polysomy) and (iii) altered ligand expression (with the possible formation of autocrine loops)." (PMID 27104520, 2016). "However, we observed that the N-glycopeptides of several cancer-associated proteins (e.g., EGFR, LGALS3BP, and PLOD3) were down-regulated in hiPSCs compared to hESCs." (PMID 27808266, 2016). "EGFR remains an important transmembrane receptor target in cancer and molecular imaging of EGFR status—expression or mutation—using PET could aid patient selection for treatment with novel reversible or irreversible inhibitors." (PMID 27552105, 2016). "Over expression of EGFR is associated with cancer development." (PMID 27287039, 2016). "In addition, personalized cancer treatments targeting the oncogenic EGFR mutations are currently developing." (PMID 27833557, 2016). "EGFR amplification or mutation occurs in multiple cancers, especially NSCLC." (PMID 27690301, 2016). "This suggests that the coexistence of EGFR activation with PTEN loss may be a common paradigm in cancer that could potentially be exploited." (PMID 27484095, 2016). "In other cancers, EGFR expression in CTCs is associated with poor prognosis and overall survival." (PMID 27916908, 2016). "Evaluation of the growth inhibitory effect of erlotinib by the SDI method revealed that cancer cell viability was reduced concentration-dependently in the EGFR mutation-positive cases but hardly in the EGFR-negative cases even at high concentration of up to 20 mM (data not shown)." (PMID 27070423, 2016).